POMC (proopiomelanocortin)
Diseases named in the same sentence as POMC in open-access papers (continued):
Sharing a sentence is not in itself a finding about the gene and the disease.
anorexia nervosa (10 papers, 2011 to 2025). A disorder most often seen in adolescent females characterized by a refusal to maintain a minimally normal body weight, an intense fear of gaining weight, a disturbance in body image, and, in postmenarcheal females, the development of amenorrhea. "As examples, oxytocin is released into the blood in response to stressful and social stimuli, and POMC methylation has been observed in the blood associated with weight loss caused by anorexia nervosa." (PMID 24112369, 2014). "On the other hand, patients with anorexia nervosa have shown significantly higher levels of POMC than controls." (PMID 36986097, 2023). "Contrary to our results, a significant negative correlation was also observed between serum POMC levels and BMI (R = −0.526, p < 0.010) in subjects with anorexia nervosa." (PMID 36986097, 2023).
Autoimmunity (10 papers, 2015 to 2025). The occurrence of an immune reaction against the organism's own cells or tissues. "Therefore, further studies are needed to clarify whether the identification of the specific site of the anti-POMC antibodies in the present analyses can facilitate the early detection of paraneoplastic autoimmune ACTH deficiency." (PMID 38035072, 2023).
schizophrenia (10 papers, 2010 to 2023). A major psychotic disorder characterized by abnormalities in the perception or expression of reality. "We found some evidence for a role of POMC in both PTSD and schizophrenia, in particular in antipsychotic-induced MetS, as well as for α-MSH in schizophrenia, but, surprisingly, no study on α-MSH in PTSD." (PMID 31798479, 2019).
Alcohol (9 papers, 2012 to 2023). "Another study found that POMC gene polymorphisms related to alcohol dependence." (PMID 35592377, 2022). "The interaction between the POMC rs2071345 genotype and alcohol dependence was significant (p = 0.03)." (PMID 35592377, 2022). "In the clinic, basal levels of plasma β-E, as well as a rise in this peptide following alcohol administration, correlate with a heritable risk for high drinking and a POMC haplotype marker has been associated with alcoholism in women, but not men." (PMID 37091593, 2023). "Moreover, the epigenetic modifications of the POMC gene can be passed down through the generations via the male germline and may be strongly involved in alcoholism-inherited disorders." (PMID 36986097, 2023).
Cachexia (9 papers, 2010 to 2026). Severe weight loss, wasting of muscle, loss of appetite, and general debility related to a chronic disease. "Indeed, during cancer-cachexia, the hypothalamus responds inadequately to neuroendocrine signals, as exemplified by the dysregulation of appetite suppressing POMC neurons and appetite stimulating NPY/AgRP neurons." (PMID 35031523, 2022). "Interestingly, cerebral treatment with LCN2 not only induced many of the observed molecular changes in cachexia but also affected gene expression in food-intake decreasing POMC neurons." (PMID 35031523, 2022). "This pathway suggests a potential mechanistic link between POMC-mediated SNS hyperactivity and the pathogenesis of cachexia." (PMID 41526343, 2026). "A primary mechanism in cancer-depended cachexia occurs through dysregulation of the hypothalamic axes related to energy uptake such as neuropeptide Y (NPY) and proopiomelanocortin (POMC)/cocaine pathways." (PMID 32466362, 2020). "LCN2 modulates gene expression in both appetite-suppressing pro-opiomelanocortin (POMC) neurons and appetite-stimulating NPY/AgRP neurons, affects immune cells, and upregulates endothelial inflammation genes and cachexia-specific oligodendrocyte genes in the hypothalamus." (PMID 40362192, 2025). "Overexpression of IL-1β in the ARC of arthritic rats on all dietary regimes indicates its role in AA- induced cachexia rather than anorexigenic neuropeptides CART and POMC." (PMID 20953376, 2010). "Independently of feeding status, AA induced cachexia, in which modulation of mRNA expressions for appetite-regulating neuropeptides (NPY, AgRP, POMC, CART) in the arcuate nucleus (ARC) does not play a primary role." (PMID 20953376, 2010).
mental disorder (9 papers, 2012 to 2024). A disease that has its basis in the disruption of mental process. "Given the links between the HPA axis, FASD and mental disorders, understanding the dysregulation of POMC through epigenetic mechanisms could lead to a better understanding of these diseases and new avenues of treatment." (PMID 24917878, 2014). "And hub proteins, such as POMC, COMT, NPS, BDNF, also have the potential to be applied as targets for the diagnosis and treatment of mental disorders." (PMID 27917343, 2016). "Furthermore, it was found that hub proteins, such as COMT, POMC, NPS and BDNF, might be the potential targets for mental disorders therapy." (PMID 27917343, 2016).
Impaired glucose tolerance (8 papers, 2018 to 2026). An abnormal resistance to glucose, i.e., a reduction in the ability to maintain glucose levels in the blood stream within normal limits following oral or intravenous administration of glucose. "This study demonstrates that EA can ameliorate HFD-induced impaired glucose tolerance through improved response of POMC neurons to Adipo in the hypothalamus, providing insight into the central mechanism of improving IR through EA." (PMID 37034166, 2023). "This latter observation suggests that pharmacological strategies that can promote G12/13 signaling in POMC neurons may prove useful to restore euglycemia under pathophysiological conditions characterized by impaired glucose tolerance." (PMID 40644553, 2025).
Infertility (8 papers, 2009 to 2025). "Consequently, POMC neurons as a target of leptin/insulin actions were shown to be important for fertility, as IR/LEPR-POMC KO mice exhibit lengthened reproductive cycles, follicular arrest, hyper-androgenemia, and infertility." (PMID 27146259, 2016).
morbid obesity (8 papers, 2009 to 2024). An excess of body weight, normally defined as an individual with a body mass index greater than 35 or a body weight greater than one hundred percent of ideal body weight. "Mutations in the POMC gene have been linked to morbid obesity." (PMID 39273520, 2024). "Furthermore, no deleterious mutations were found in genes known to cause morbid obesity such as leptin, leptin receptor, melanocortin 4 receptor, POMC, adiponectin and adiponectin receptor." (PMID 23300646, 2012). "Although disruption of the STAT3 binding site in LepRb or deletion of neuronal STAT3 results in severe hyperphagia and morbid obesity, deletion of STAT3 in either POMC or AgRP neurons only slightly increases food intake and adiposity in mice." (PMID 22291999, 2012).
overnutrition (8 papers, 2011 to 2025). An imbalanced nutritional status resulting from excessive intake of nutrients. "Maternal overnutrition was associated with long-term epigenetic alterations in the offspring’s hypothalamic Proopiomelanocortin (POMC) promoter." (PMID 34579008, 2021). "Mitochondrial stress in POMC neurons has been suggested as a possible mechanism underlying this neuronal loss, as well as IKKb NF‐kB activation and ER stress in hypothalamic neurons induced by overnutrition." (PMID 35603807, 2022). "Hypothalamic AgRP and POMC are ‘yin/yang’ master regulators that promote/inhibit food intake, previous studies observed a higher ratio of AgRP/POMC expressing neurons in offspring raised by mothers with maternal overnutrition during pregnancy and/or lactation." (PMID 38493217, 2024). "Maternal obesity, overnutrition, or inflammation can durably alter AgRP and POMC connectivity through microglial activation and impaired perineuronal net (PNN) maturation, establishing a “metabolic memory” that predisposes offspring to lifelong glucose dysregulation." (PMID 41409607, 2025). "We previously demonstrated that intrauterine and early postnatal overnutrition due to litter size reduction altered the expression of NPY and POMC in offspring at weaning, as well as their response to fasting." (PMID 21980407, 2011). "In rats, we previously showed that intrauterine and early postnatal overnutrition altered the expression of hypothalamic appetite stimulator neuropeptide Y (NPY) and suppressor pro-opiomelanocortin (POMC) in offspring at weaning." (PMID 21980407, 2011). "It is possible that maternal obesity and overnutrition influenced the hypothalamic synaptic inputs of NPY and POMC neurons, which we did not investigate, rather than neuropeptide expression of NPY and POMC, which we did report." (PMID 32987812, 2020).
systemic lupus erythematosus (8 papers, 2015 to 2025). An autoimmune multi-organ disease typically associated with vasculopathy and autoantibody production. "Among these genes, POMC produces peptides involved in anti-inflammatory actions, BANK1 is associated with systemic lupus erythematosus, and MAST3 and AHSA2 are associated with IBD, corroborating the role of immunity-related genes in shaping gut microbiota." (PMID 37081571, 2023).
Genetic obesity (7 papers, 2021 to 2026). "Setmelanotide is successful in the treatment of genetic obesity (e.g., POMC deficiency), indicating its potential effect in HO." (PMID 41601974, 2026). "Given the pivotal roles of ER quality control system in aberrant protein clearance, it is worth exploring whether the enhancement of ERAD or ER-phagy activity may efficiently treat genetic obesity caused by POMC mutations." (PMID 37152279, 2023). "Therefore, setmelanotide is indicated in patients with genetic obesity due to either the defect in the pro-opiomelanocortin (POMC) gene, Leptin receptors (LEPR)gene, and the proprotein convertase subtilisin/kexin type 1 (PCSK1) gene." (PMID 38715796, 2024). "However, the setmelanotide treatment is offered only for the mitigation of secondary symptoms of genetic obesity without removing the POMC gene mutation." (PMID 37152279, 2023). "Therefore, more structural and protein interaction studies are required to further clarify the roles of POMC-derived neuropeptides, MC3R, and MC4R in genetic obesity." (PMID 40001512, 2025).
malnutrition (7 papers, 2013 to 2026). Inadequate nutrition resulting from poor diet, malabsorption, or abnormal nutrient distribution. "Thus, it has been shownin laboratory models and humans that the metabolic state ofmothers during pregnancy (malnutrition, overeating) affectsmethylation of the gene encoding proopiomelanocortin and,accordingly, its expression in the hypothalamus in the offspring." (PMID 38952707, 2024). "No significant group differences were found for AgRP and POMC, although AgRP tended to be lower and POMC higher in the malnutrition group." (PMID 41683201, 2026). "Thus, in a situation of negative energy balance, such as the malnutrition observed in ALS, the expression of NPY and AgRP is normally increased and POMC expression decreased." (PMID 34638645, 2021).
psoriasis (7 papers, 2015 to 2025). An autoimmune condition characterized by red, well-delineated plaques with silvery scales that are usually on the extensor surfaces and scalp. "The restoration of these endogenous deficiencies (i.e., boosting local steroidogenesis and the effects of POMC/glucocorticoids) is seen as a “realistic target” for treating psoriasis and other inflammatory skin disorders." (PMID 40650250, 2025).
vitiligo (7 papers, 2008 to 2025). Generalized well circumscribed patches of leukoderma that are generally distributed over symmetric body locations and is due to autoimmune destruction of melanocytes. "The expression of both POMC and MC1‐R were significantly lower in the lesional skin, compared with both the non‐lesional skin of vitiligo cases, as well as compared with the controls, while they were significantly higher in non‐lesional vitiligo skin than in controls." (PMID 37275429, 2023). "Vitiligo is a cutaneous autoimmune disease of acquired pigmentary disorder, additionally, there are lower gene expressions of the melanocortin receptors (including MC1R and MC4R) and POMC in vitiliginous lesion skin compared to the nonlesional skin due to the loss of functional melanocytes." (PMID 35805166, 2022).
endotoxemia (6 papers, 2016 to 2024). "Here, we compared the effect of low-calorie, medium-calorie and high-calorie EN on hypercatabolism in the acute phase of endotoxemia, which is associated with gastrointestinal hormones and hypothalamic neuropeptide proopiomelanocortin (POMC)." (PMID 35428321, 2022). "Taken together, these results suggest activation of hypothalamic POMC is pivotal for acute muscle wasting caused by endotoxemia." (PMID 27922103, 2016). "In endotoxemia rats, the LPS + L group exhibited more obvious effects in terms of reducing POMC level compared with the LPS + M and LPS + H groups." (PMID 35428321, 2022). "In the endotoxemia group in our study, the hypothalamic inflammation was also related to the alterations of the mRNA expression of POMC and AgRP, which was consistent with former studies." (PMID 28358856, 2017). "Because we have shown the importance of hypothalamic NF-κB pathway in endotoxemia-induced muscle wasting, we investigated whether the protective effect of knockdown POMC on muscle wasting was related NF-κB." (PMID 27922103, 2016). "Additionally, the expressions of POMC and CART were significantly increased in endotoxemia." (PMID 35428321, 2022).
LEPR deficiency (6 papers, 2020 to 2025). "In a natural history study of patients with POMC or LEPR deficiency, 2 of 8 patients with LEPR deficiency reported previous unsuccessful attempts to lose weight with methylphenidate or dextroamphetamine, although the impact on hyperphagia was not reported." (PMID 40560452, 2025). "Overall, patients with POMC deficiency appear to respond the best to setmelanotide, followed by patients with LEPR deficiency and patients with BBS." (PMID 39526054, 2024). "Very little research exists on the impact of POMC or LEPR deficiency on QOL." (PMID 35123544, 2022). "The MC4R agonist, setmelanotide, should be administered in patients with POMC, PCSK1, or LEPR deficiency and BBS, and the GLP-1 receptor agonists, semaglutide and liraglutide are also novel pharmacological agents that have been FDA approved for the treatment of childhood obesity." (PMID 38397265, 2024).
neuroblastoma (6 papers, 2013 to 2025). Neuroblastoma (NB) is the most common solid, extracranial childhood tumor. "Adiponectin is also expressed in two neuronal cell lines: mHYPO POMC (adult mouse hypothalamic neuronal cell line) and SH-SY5Y (human neuroblastoma cell line)." (PMID 36078135, 2022). "Adiponectin expression is also evidenced in two neuronal cell lines mHypo POMC (an adult mouse hypothalamic cell line) and SH-SY5Y (human neuroblastoma)." (PMID 36078135, 2022). "The constructs were then transiently transfected into mouse neuroblastoma Neuro2a cells for 48 h before co-immunostaining for the Myc tag and RCAS1 (Golgi marker) or PDI (Endoplasmic Reticulum marker) or POMC (neuropeptide vesicle marker)." (PMID 31974728, 2020).
Alzheimer disease (5 papers, 2013 to 2022). A progressive, neurodegenerative disease characterized by loss of function and death of nerve cells in several areas of the brain leading to loss of cognitive function such as memory and language. "Expression of an Alzheimer amyloid secretase pathway suggests participation of POMC neurons in the pathogenesis of diabetic comorbidities in Alzheimer’s disease." (PMID 27609221, 2016).
atherosclerosis (5 papers, 2015 to 2023). A disease characterized by the build-up of fatty material and calcium deposition in the arterial wall resulting in partial or complete occlusion of the arterial lumen. "Further research will be fundamental to explore how atherosclerosis affects POMC processing in mice and humans." (PMID 30305673, 2018). "The present study aimed at investigating the expression of POMC and POMC-related enzymes in human atherosclerosis." (PMID 30305673, 2018). "This notion is supported by the finding of discordant POMC and α-MSH expression levels in the aorta of Apoe−/− mice, i.e. increased POMC and falling α-MSH level in response to diet-induced atherosclerosis." (PMID 30305673, 2018). "Here we investigated the regulation of POMC and α-MSH expression in atherosclerosis." (PMID 30305673, 2018). "The expression level of POMC in carotid or abdominal samples was not significantly different in comparison with atherosclerosis-free left internal thoracic artery (LITA) samples." (PMID 30305673, 2018).
Failure to thrive (5 papers, 2021 to 2025). Failure to thrive (FTT) refers to a child whose physical growth is substantially below the norm. "In a transgenic mouse model of PWS, which displayed failure to thrive during the neonatal period, the expression of AgRP mRNA was decreased while the mRNA expression of POMC was upregulated in PWS-mice neonates." (PMID 40136445, 2025). "Since AgRP stimulates appetite and the POMC-derived peptide, α-MSH, stimulates satiety, these changes together will decrease feeding and may thus contribute to the failure to thrive in PWS neonatal mice." (PMID 40136445, 2025).
hyperlipidemia (5 papers, 2018 to 2023). "Proopiomelanocortin (POMC), an appetite-inhibiting neuropeptide, is decreased by increased levels of appetite-stimulating neuropeptides such as neuropeptide Y (NPY) and agouti-related peptide (AgRP), which reduces energy expenditure, increases food intake, weight gain, and hyperlipidemia." (PMID 37425327, 2023).
migraine (5 papers, 2019 to 2025). "Several previous studies have shown that peptides from prohormones such CGRP (in plasma and TG), NPY (in dorsal root ganglia and DH), and PENK/POMC (in H) are directly associated with migraine and other pain states." (PMID 31649062, 2019). "And estrogen affects energy homeostasis via the proopiomelanocortin (POMC) neurons in the hypothalamic arcuate, and may play a role in migraine." (PMID 38392617, 2024).
neuroendocrine carcinoma (5 papers, 1988 to 2023). A malignant neuroendocrine neoplasm composed of cells containing secretory granules that stain positive for NSE and chromogranin. "In this study, we conducted REST gene editing and PROX1 transgene analysis and attempted to utilize the transgene pro-opiomelanocortin (POMC) as an intragranular molecule to define suitable conditions for producing ESGs using the undifferentiated non-neuroendocrine cancer cell line H1299." (PMID 35094211, 2022).
Prader-Willi syndrome (5 papers, 2013 to 2025). "In Prader-Willi Syndrome, loss of MAGEL2 may likewise abolish leptin responses in POMC hypothalamic neurons." (PMID 23341784, 2013).
skin cancer (5 papers, 2010 to 2025).
thyroid cancer (5 papers, 2020 to 2023). "Out of 28 protein-coding, five genes; TERT, FLT4, DUSP6, USP10 and POMC have already been implicated in thyroid cancer." (PMID 32324757, 2020).
vitamin D deficiency (5 papers, 2012 to 2025). A nutritional condition produced by a deficiency of VITAMIN D in the diet, insufficient production of vitamin D in the skin, inadequate absorption of vitamin D from the diet, or abnormal conversion of vitamin D to its bioactive metabolites. "It has been suggested that vitamin D deficiency increases appetite and decreases energy consumption by stimulating Agouti Related Protein/Neuropeptide Y (AgRP/NPY) and suppressing the pro-Opiomelanocortin/Cocaine-Amphetamine-Regulated Transcription (POMC/CART) pathway." (PMID 29281967, 2017).